SOX10 (SRY-box transcription factor 10)
Diseases named in the same sentence as SOX10 in open-access papers (continued):
Sharing a sentence is not in itself a finding about the gene and the disease.
melanoma (continued). "The presence of phosphorylation sites within these domains were of particular interest because of the importance of the MAPK pathway in melanoma progression, and the potential involvement of SOX10 protein in acquired resistance to MAPK inhibitors." (PMID 29315345, 2018). "Single IF slides were stained for PD-1, PD-L1, CD8, FoxP3, CD163, and a tumor marker (e.g. Sox10/S100 for melanoma) using primary antibodies at manufacturer’s recommended concentrations and visualized with an Opal kit (PerkinElmer)." (PMID 30400835, 2018). "While the importance of SOX10 in embryonic development and melanoma progression has been well recognized, the regulation of SOX10 remains poorly characterized." (PMID 29295999, 2018). "SOX10 expression was depleted using two independent SOX10-specific siRNAs in mutant BRAF melanoma cells which were then treated with the RAF inhibitor, Vemurafenib, for various times." (PMID 29295999, 2018). "Generation of mutants at amino acids S24, S45 and T240, each located in predicted MAPK/CDK binding motifs, allowed investigation of their effect on SOX10 transcription activity, subcellular localization, and stability in melanoma cells." (PMID 29315345, 2018). "Expression of WT HA-SOX10 efficiently rescued FOXD3 induction by ERK inhibition in melanoma cells depleted of endogenous SOX10." (PMID 29295999, 2018). "This mode of Sox5 and Sox10 interaction has been reported in mouse melanocytes and in human melanoma cells, suggesting that an antagonistic interaction between Sox5 and Sox10 is widely conserved among vertebrates." (PMID 29621239, 2018). "It will also be of great interest to determine in future studies if the SOX10 phosphorylation demonstrated here in melanoma can be extended to breast carcinomas and other cancers that maintain SOX10 expression." (PMID 29315345, 2018). "Here, we present data that support phosphorylation as a mechanism employed by melanoma cells to tightly regulate SOX10 expression." (PMID 29315345, 2018). "Our analysis supports and extends this data, identifying T240 phosphorylation in melanoma cells and demonstrating decreased protein stability of SOX10 T240A compared to WT protein, as assayed in MeWo melanoma cells." (PMID 29315345, 2018). "This study identifies eight SOX10 protein phosphorylation sites by mass spectrophotometry in melanoma cells." (PMID 29315345, 2018). "SOX10 mutations were generated at these phosphorylation sites to assess their impact on SOX10 protein function in melanoma cells, including transcriptional activation on target promoters, subcellular localization, and stability." (PMID 29315345, 2018). "The suppression of SOX10 in melanoma cells activates TGF-β signaling and can promote resistance to BRAF and MEK inhibitors." (PMID 29315345, 2018). "Our work completes an ERK/SOX10/FOXD3/ERBB3 pathway that governs the FOXD3-mediated adaptive resistance to RAF/MEK inhibitors in mutant BRAF melanoma." (PMID 29295999, 2018). "SOX10 knockdown alone inhibited melanoma cell growth but only had a moderate influence on apoptosis." (PMID 29295999, 2018). "At the immunohistochemical level, positivity for SOX10 is an essential marker to distinguish desmoplastic melanoma from these other tumors." (PMID 29156643, 2017). "This last was human malignant melanoma cells, and was the only cell type expressing SOX10 at the protein level." (PMID 28683107, 2017). "This transition indicates that a fate change occurs at the initiation of the melanoma tumorigenic process, orchestrated by the SOX10 transcription factor." (PMID 29156643, 2017). "This is also the case for zebrafish melanomas and human melanoma lines, which share super-enhancer signatures for the neural crest transcription factors Sox10 and Dlx2." (PMID 28894696, 2017). "Suppression of SOX10 in a proportion of melanomas can lead to TGF-β signaling and consequently to EGFR and platelet-derived growth factor receptor-β (PDGFRB) upregulation, conferring oncogene-induced senescence." (PMID 29100459, 2017).
melanoma (continued). "This conclusion was reached through CD271 knockdown experiments showing a reduced expression of the transcription factors SOX10 (whose expression was required for maintenance of melanoma CSCs) and MITF (required for melanoma proliferation and invasiveness)." (PMID 29156643, 2017). "A recent study partly clarified the molecular mechanisms through which SOX10 promotes melanoma development." (PMID 29156643, 2017). "The functional relevance of reactivating neural crest identity was demonstrated in an experiment showing that overexpression of the neural crest regulator Sox10 in melanocytes accelerated melanoma formation." (PMID 28894696, 2017). "Strikingly, we obtained very good prediction results (PCC r = 0.76) by using the optimization parameters of the SOX5/SOX10 model learned on the NCI-60 data for the prediction of MITF levels of the independent melanoma data set (33 melanoma samples)." (PMID 26927636, 2016). "MITF regulation by SOX5 has only been shown in murine cells so far and hence we were interested in the regulatory effect of SOX5 on MITF in human melanoma cells and tumors, and its regulatory effect in combination with SOX10." (PMID 26927636, 2016). "In this work, we describe the detection of SOX10 in blood serum from vitiligo and melanoma patients." (PMID 27110718, 2016). "In a model expressing activated mutant BRAFV600E, re-expression of crestin marked the earliest events in melanoma formation, and overexpression of Sox10 accelerated the formation of melanomas." (PMID 27655644, 2016). "In melanoma, SOX10 functions both independently and in cooperation with MITF to promote more differentiated and/or proliferative cellular states." (PMID 27852308, 2016). "SOX10 suppression contributes to BRAF- and/or MEK-inhibitor resistance in BRAF mutated melanoma, by activating TGFβ signalling to upregulate EGFR and PDGFRB, whilst increasing SOX9 transcript abundance has been observed in breast cancer EMT." (PMID 27852308, 2016). "Sox10, Pax3 and Mitf genes are key regulators of melanocyte development, and regulate Met expression in melanocytes and melanoma cells." (PMID 27683122, 2016). "We show for the first time that SOX10 represents a promising new serum melanoma marker for detection of early stage disease, complementing the established S100B marker." (PMID 27110718, 2016). "In contrast, elevated serum SOX10 was found with high frequency among vitiligo and melanoma patients." (PMID 27110718, 2016). "This study, where Proximity ligation assay is applied to detect SOX10 in serum for the first time is focus on melanoma patients." (PMID 27110718, 2016). "By using a novel SOX10 proximity ligation assay we demonstrate in this study for the first time that elevated levels of SOX10 is detected in the serum from melanoma patients." (PMID 27110718, 2016). "Recent reports have revealed that MIA expression is induced by binding of SRY (sex-determining region Y)-box 10 (SOX10) to the MIA promoter region in malignant melanoma." (PMID 27050375, 2016). "We detected elevated levels of both SOX10 and S100B, both in groups with thin melanoma in situ and in later stages of the disease." (PMID 27110718, 2016). "A SOX10-low state is associated with reduced cell proliferation and engagement of EMT-like processes in melanoma to promote more invasive phenotypes - a state maintained, in part, through mutual-antagonism with the closely related transcription factor SOX9." (PMID 27852308, 2016). "In this study we have applied proximity ligation assay (PLA) to detect the transcription factor SOX10 as a possible serum marker for melanoma." (PMID 27110718, 2016). "Expression of mitfa is regulated by sox10, a transcription factor expressed in neural crest cells and re-expressed during melanoma initiation." (PMID 27655644, 2016). "Recently, the transcription factor Sox10 has been shown to promote both melanoma initiation and progression." (PMID 25629959, 2015).
melanoma (continued). "Genes upregulated in this cluster include known markers of the melanocyte lineage and melanoma such as SOX10, MITF and PAX3." (PMID 25865119, 2015). "More importantly, we found that Fbxw7α suppresses melanoma cell migration by promoting SOX10 proteolysis." (PMID 26461473, 2015). "This is in accordance with our previously published results on the essential role of SOX10 for melanoma initiation and progression." (PMID 25629959, 2015). "Taken together, these results indicate that Fbxw7α regulates the endogenous expression of SOX10 in melanoma cells." (PMID 26461473, 2015). "In a recent example, Soengas and colleagues identified RAB7 as a new regulator of melanoma progression and showed this to be specifically wired into the melanoma lineage by the transcription factors SOX10 and MYC." (PMID 25670789, 2015). "Here we show that in contrast to Sox10, Sox9 appears to be expressed at very low levels only and is functionally not required in melanocyte stem cells, committed melanocytes, and melanoma cells." (PMID 25629959, 2015). "Although SOX-10 has been proven to be a superior marker for melanoma in skin, benign melanocytic lesions also express SOX-10; therefore, SOX-10 cannot be used to differentiate benign from malignant melanocytic skin lesions." (PMID 26316887, 2015). "Reducing SOX10 expression levels in human melanoma cells and in a genetic melanoma mouse model, efficiently abolishes tumorigenesis by inducing cell cycle exit and apoptosis." (PMID 25629959, 2015). "Cells from giant congenital naevi showed a 5-fold increase in SOX10 expression when compared to normal melanocytes, while M010817 melanoma cells displayed a 10-fold increase in SOX10 expression when compared to normal melanocytes." (PMID 25629959, 2015). "Among others, these data suggest that while SOX10 acts as an inhibitor of apoptosis in melanoma cells, SOX9 elicits a proapoptotic response." (PMID 25629959, 2015). "Similar findings by the Pavan laboratory demonstrate that SOX10 haploinsufficiency prevents melanoma formation in a Grm1-transgenic mouse melanoma model." (PMID 25670789, 2015). "To further investigate the regulatory relationship between Fbxw7α and SOX10, we first examined the endogenous interaction between Fbxw7α and SOX10 in melanoma cells." (PMID 26461473, 2015). "To further investigate the specificity of anti-SOX9 antibodies, we performed SOX10 knockdown in human melanoma cell lines in vitro and analyzed SOX10 and SOX9 expression using Western blot analysis." (PMID 25629959, 2015). "SOX10 was found to be overexpressed in many cancers, including melanoma, schwannoma, neurofibroma, salivary gland tumors, astrocytoma and glioma." (PMID 26461473, 2015). "This is in analogy to the upregulation of SOX9 mRNA previously observed in melanoma cells upon SOX10 knockdown." (PMID 25629959, 2015). "More recently, a critical role for SOX10 in tumorigenesis and melanoma migration has been demonstrated in cell lines and mouse models." (PMID 26461473, 2015). "Of note, the anti-tumorigenic effect elicited by suppressing SOX10 was abolished by concomitant SOX9 inactivation both in human melanoma cells as well as in mice." (PMID 25629959, 2015). "MIA was reported to be a transcriptional target of SOX10 and responsible for SOX10 mediated melanoma migration." (PMID 26461473, 2015). "As in human melanoma cells in vitro, reducing Sox10 levels in vivo elicits an anti-tumorigenic effect, preventing melanocytic hyperplasia in Tyr::NrasQ61KSox10fl/+Tyr-CreERT2 mice." (PMID 25629959, 2015). "ATF2 (activating transcription factor 2) displays inhibitory activity towards SOX10 both in melanocytes and melanoma cells, resulting in a decreased MITF transcript level." (PMID 25433395, 2015). "We show that a transcription factor called SOX10 promotes melanoma formation by repressing an anti-tumorigenic program involving the activity of a related factor, SOX9." (PMID 25629959, 2015).
melanoma (continued). "We also show that Fbxw7α suppressed the SOX10-mediated migration-promoting effect on melanoma cells." (PMID 26461473, 2015). "While SOX10 expression and function has been well established in adult melanocytes, naevi, and melanoma tissue in human and mice, studies on SOX9 expression in melanocytic cells are controversial." (PMID 25629959, 2015). "Analysis of mRNA expression levels of CD271, CD133, ABCB5, SOX2 and melanoma markers SOX10, NES and TYR, MART-1 and MITF-M revealed a strong heterogeneity among the PM tissue samples." (PMID 24799129, 2014). "In melanoma, SOX10 haploinsufficiency abrogates NrasQ61K-driven tumor initiation as well as progression." (PMID 25301735, 2014). "SOX10 silencing in human melanoma cells suppresses neural crest stem cell properties, counteracts proliferation and cell survival, and completely abolishes in vivo tumor formation." (PMID 24743024, 2014). "SOX10 was reported to possess tumor-promoting activities in several malignancies including melanoma and gliomas." (PMID 25301735, 2014). "Like CD271 and CD133 in melanoma-initiating cells, SOX10 expression maintains the multipotent phenotype of NCSCs and the tumorigenic and proliferative capacity of melanoma cells." (PMID 24799129, 2014). "That screen identified the SRY (sex determining region Y)-box 10 (SOX10) gene as a regulator of EGFR expression in four different tested melanoma cell lines." (PMID 25031620, 2014). "In summary, the regulation of SOX10 expression in melanoma is supposedly comparable with the mechanism that controls SOX10 during development and specification of the neural crest." (PMID 24799129, 2014). "The translational importance of Sox10 in melanocytic disease is highlighted in recent studies linking Sox10 with cell cycle regulation and reduction of SOX10 expression correlating with reduced tumor cell burden in a mouse melanoma model." (PMID 23935512, 2013). "SOX9 protein was strongly present in melanoma cells, and weakly detected in colon cancer and mesothelioma cell lines whereas SOX10 expression was restricted to melanoma cell lines." (PMID 24086527, 2013). "Among them, those participating in melanocyte differentiation and melanogenesis belong to the SOX-E group, including SOX9 and SOX10, both expressed in established melanoma cell lines." (PMID 24086527, 2013). "We therefore endeavoured to formally demonstrate the implication of CREB, SOX9 and SOX10 factors in meloe promoter activity, first by evaluating their expression in melanoma cells." (PMID 24086527, 2013). "This in turn indicates that in order to analyze the role of Sox10 in migration and isolate relevant down-stream target genes, it is necessary to select an appropriate melanoma cell line." (PMID 22363655, 2012). "We examined two other mouse melanoma cell lines, Cloudman S91 and Melan-a for the involvement of Sox10 in migration." (PMID 22363655, 2012). "Given the effect of differentiation program inherent to melanocytes on migration and metastasis, we sought to determine if Sox10 regulates migration and metastatic behaviors of melanoma." (PMID 22363655, 2012). "In this regard, B16F10 melanoma cells, highly migratory and impervious to down-regulation of Sox10 and Mitf for survival at least short term, have been useful." (PMID 22363655, 2012). "As expected, luciferase activation was higher in melanoma than in HeLa cells due to the cooperation of melanocyte specific components (Sox10 and Pax3), cAMP signaling machinery and the physiological tissue-specific expression of the M-Mitf promoter." (PMID 22427932, 2012). "Two of them, U1 and U3, which are localised 55 kb and 33 kb upstream of the SOX10 gene respectively, drive SOX10/Sox10 expression during melanocyte development in particular, at least in zebrafish and in melanoma cells (and our unpublished results)." (PMID 22848661, 2012).
melanoma (continued). "In this study, we show that the cascade of gene expression initiated by Sox10 and subsequently mediated in part by Mitf likely represents an important regulatory axis of migration and metastasis in a subset of melanoma cases." (PMID 22363655, 2012). "Secondly, in a recent study, Agnarsdottir and co-workers showed that down-regulation of Sox10 differentially affects migration in different melanoma cell lines." (PMID 22363655, 2012). "Here, we used RNA interference technique to demonstrate the role of Sox10 on migration in B16F10 melanoma cells and to identify its potential transcriptional regulatory targets." (PMID 22363655, 2012). "This seems to indicate that much of the effect of Sox10 on melanoma migration is in fact mediated by Mitf although an exhaustive study needs to be carried out with more genes from the microarray screen." (PMID 22363655, 2012). "We first sought to determine if Sox10 is involved in regulating migratory behavior of B16F10 melanoma cells." (PMID 22363655, 2012). "Sox10, a transcription factor, presumably regulates the expression of other genes that function as the “effector” genes of migration of melanoma cells." (PMID 22363655, 2012). "In contrast however, an average of 5% (range: 0%–9.5%; SD: 4.3) and 3% (range: 0%–9%; SD: 2.9) of the neoplastic Sox10 -positive melanoma in situ and invasive melanoma cells, respectively, were ciliated." (PMID 22096570, 2011). "In agreement, chromatin immunoprecipitation (ChIP) assays confirmed increased binding of SOX10 to the MITF promoter in melanoma cells expressing shATF2." (PMID 21203491, 2010). "In agreement, inhibition of SOX10 expression by corresponding siRNA attenuated the increase in MITF transcription seen in shATF2-expressing human melanocytes or melanoma cells." (PMID 21203491, 2010). "SOX10 was unmethylated (<2%) in two pigmented melanoma cell lines (M624 and M888) and methylated (95%) in a breast cancer cell line (MCF7)." (PMID 16457718, 2006). "The melanocyte lineage appears to be infrequent in plucked hairs because only one of 234 SOX10 tags sampled after two years of age was unmethylated like the melanoma cell lines." (PMID 16457718, 2006). "Dlx4os knockdown redirected melanoma cells to a more differentiated and less malignant phenotype, confirmed by differential expression of phenotypic state markers (Sox10, Mitf, Tgfβ, Sox6, Mlana), reduced their invasive and migratory potential, and delayed tumour progression in vivo." (PMID 41855479, 2026). "Hence, we propose that SOX10 plays a positive role in the infiltration of NK cells into melanoma tissue." (PMID 40342816, 2025). "Classically, they are biphasic tumors composed of an element of conventional melanoma with retained melanocytic markers (e.g., SOX10, S‐100, Melan‐A, and HMB45) and an adjacent population of cytologically distinct cells that lack any evidence of melanocytic differentiation." (PMID 40090763, 2025). "To determine whether HK2 could specifically associate with the SOX10 mRNA, we performed HK2 immunoprecipitation (IP) followed by RT-qPCR (RNA ImmunoPrecipitation-RIP analysis) in A375 and A2058 melanoma cells." (PMID 40956859, 2025). "Immunohistochemically, the tumor cells were positive for S100 (5/6), cyclin D1 (2/3), SATB2 (2/3), BCOR (2/4), and TLE1 (1/3) while negative for MUC4 (0/6), keratin (0/5), EMA (0/4), desmin (0/6), CD34 (0/6), SMA (0/5), SOX10 (0/5), and melanoma cocktail (0/2)." (PMID 40705064, 2025). "As observed in our case, S100-negative melanomas frequently retain SOX10 and MITF expression." (PMID 41458594, 2025). "Finally, reprogramming to an immature state enables AML cells to evade differentiation therapy, and melanoma cells exposed to treatment downregulate SOX10, hence limiting SOX10-mediated differentiation in support of chemoresistance." (PMID 40744921, 2025).